PSD3 (pleckstrin and Sec7 domain containing 3)
Diseases named in the same sentence as PSD3 in open-access papers (continued):
Sharing a sentence is not in itself a finding about the gene and the disease.
tumor (6 papers, 2017 to 2025). "PSD3 appears to skew the tumor milieu toward immune suppression, while CD274 is linked to both stimulatory and suppressive immune components." (PMID 40895529, 2025). "The apparent paradox—where higher PSD3 expression is linked to improved survival despite its tumor-promoting functions in vitro—may reflect the gene’s context-dependent roles." (PMID 40895529, 2025). "Another consideration is that PSD3’s association with favorable prognosis may be confounded by subtype-specific tumor biology or treatment sensitivity." (PMID 40895529, 2025). "In addition to spatial correlation data, our in vitro experiments using murine ESCC cells provide the first functional evidence that PSD3 plays a causative role in driving tumor aggressiveness." (PMID 40895529, 2025). "TNFSF18, a member of the tumor necrosis factor superfamily known to modulate T cell activity, was selected based on its emerging links to tumor immunity and its co-regulation patterns with PSD3." (PMID 40895529, 2025). "It allows for the dynamic assessment of PSD3’s role in tumor growth, immune cell infiltration, and potential response to immunotherapy in a physiologically relevant, immune-intact host environment." (PMID 40895529, 2025). "Given that PSD3 appears to have immunological relevance, particularly in shaping immune evasion and tumor-immune interactions, the use of a murine model provides a crucial advantage for future mechanistic studies." (PMID 40895529, 2025). "These distinct enrichment profiles underscore the divergent functional landscapes of these genes: PSD3 appears to drive tumor-intrinsic processes, while CD274 and TNFSF18 modulate tumor-immune interactions." (PMID 40895529, 2025). "Collectively, these findings support a dual functional role for PSD3 in ESCC: promoting oncogenic behavior while concurrently influencing the immunological phenotype of tumor cells through modulation of PD-L1." (PMID 40895529, 2025). "CD274 and TNFSF18 were consistently up-regulated in tumor tissues across both TCGA and GEO cohorts, whereas PSD3 exhibited a context-dependent pattern, showing significant up-regulation in TCGA but no differential expression in GEO." (PMID 40895529, 2025). "Functional assays revealed that PSD3 promotes tumor cell proliferation, migration, and invasion while negatively regulating PD-L1 expression." (PMID 40895529, 2025). "The “circRNA pleckstrin and Sec7 domain containing 3 (circ_PSD3)” were aberrantly upregulated in PTC tumor tissues compared with adjacent normal tissues." (PMID 36230649, 2022). "We analyzed the data and found that the expression of PSD3 in PTC tissues is higher than normal tissues (Tumor tissue, 24.78 ± 0.6619, n=502; Normal tissue, 7.181 ± 0.505, n=58; P<0.0001)." (PMID 34405004, 2021). "In addition to prognostic relevance, our ROC curve analyses showed that PSD3, CD274, and TNFSF18 exhibit moderate to high diagnostic accuracy in distinguishing tumor tissues from normal controls." (PMID 40895529, 2025). "The spatially distinct and negatively correlated expression patterns suggest that PSD3 may exert an inhibitory effect on PD-L1, potentially modulating the tumor’s capacity for immune evasion." (PMID 40895529, 2025). "Functionally, PSD3 depletion led to substantial decreases in colony formation (~45%), EdU incorporation (~38%), migration (~42%), and invasion (~50%), demonstrating its role in tumor aggressiveness." (PMID 40895529, 2025). "Such compartmentalized, negatively correlated expression patterns may hint at a functional interplay or regulatory divergence between PSD3 and PD-L1 in shaping the tumor immune microenvironment." (PMID 40895529, 2025). "PSD3’s involvement in immune regulation remains less clear; however, its strong correlation with immune cell infiltration and immune pathway enrichment suggests a previously underappreciated role in modulating the tumor immune landscape." (PMID 40895529, 2025).
tumor (continued). "Circ_PSD3 silencing hampered tumor growth in vivo and facilitated apoptosis in vitro." (PMID 36230649, 2022). "PSD3 is overexpressed in HCC, demonstrating tumor-promoting effects of PSD3." (PMID 32764824, 2020). "This integrated approach enables a more comprehensive understanding of PSD3, CD274, and TNFSF18 in the context of the ESCC tumor immune microenvironment." (PMID 40895529, 2025). "Further dissection of immune cell-type correlations provided additional insight into how PSD3, CD274, and TNFSF18 may shape the tumor immune microenvironment (TME) in ESCC." (PMID 40895529, 2025). "Importantly, mIHC confirmed an inverse spatial correlation between PSD3 and CD274 protein expression in tumor tissues, suggesting potential regulatory crosstalk relevant to immune evasion." (PMID 40895529, 2025). "Interestingly, despite their central roles in anti-tumor immunity, our in silico analyses did not reveal significant correlations between the expression of PSD3, CD274, or TNFSF18 and the infiltration of CD8+T cells or natural killer (NK) cells." (PMID 40895529, 2025). "For example, increased immune infiltration associated with high gene expression might not be causally mediated by PSD3, CD274, or TNFSF18, but rather reflect a broader inflammatory state of the tumor." (PMID 40895529, 2025).
PSD3 also shares sentences with these, for which no sentence is quoted: Obesity (4 papers); acute myeloid leukemia (3); type 2 diabetes (3); schizophrenia (2); anorexia nervosa (1); autism spectrum disorder (1); bipolar disorder (1); Dravet syndrome (1); fibrosis (1); Hepatic steatosis (1); Idiopathic Peripheral Autonomic Neuropathy (1); immune disease (1); ischemia (1); liver cancer (1); neurodegenerative disease (1); ovarian carcinoma (1); polyneuropathy (1); thyroid tumor (1).